CCN4 (cellular communication network factor 4)
Diseases named in the same sentence as CCN4 in open-access papers (continued):
Sharing a sentence is not in itself a finding about the gene and the disease.
cancer (76 papers, 2003 to 2026). A tumor composed of atypical neoplastic, often pleomorphic cells that invade other tissues. "The local structure associated with “Cancer”’s influence on the “Mesenchymal” state via “CCN4” suggests an incoherent type-3 feed-forward motif to regulate the mesenchymal state." (PMID 35418177, 2022). "Similar to other CCN family members, CCN4 mRNA levels and their association with prognosis vary across different types of cancer." (PMID 33833779, 2021). "When evaluating the association between CCN4 expression and prognosis in pan-cancer, we found that high CCN4 expression was associated with shorter OS in five types of cancer (ACC, KICH, LGG, MESO, STAD)." (PMID 33833779, 2021). "CCN4 is of particular interest in cancer, as it shows promise as a biomarker or prognostic factor as well as a potential therapeutic target." (PMID 40812788, 2025). "For example, in breast and ovarian cancer models, some studies showed a beneficial effect of CCN4 in reducing cancers, while others demonstrated the opposite." (PMID 39276419, 2024). "The role of CCN4 in cancer appears to be dependent on both the cell type and model utilised, and consequently further research is required to clarify its role in these models." (PMID 39276419, 2024). "The posterior distributions mirror the experimental data points, where there is an increase in CCN4 expression between normal (“Cancer” < 0.05) and cancer (“Cancer” > 0.95) tissue." (PMID 35418177, 2022). "As there was more data supporting the BRCA DAG, the resulting Bayesian network model was compared against the underlying experimental data and used to explore the impact of varying CCN4 expression in the context of normal and cancer tissue." (PMID 35418177, 2022). "The prevalence of CD8 T cells are also connected to “Cancer” via a larger incoherent feed-forward motif involving “p(M1)”, “CCN4”, the “Mesenchymal” state, and “CAFs” with high confidence." (PMID 35418177, 2022). "Evidence also showed that CCN4 represses E cadherin activity and facilitates N cadherin, snail and β catenin upregulation, consequently facilitating cancer metastasis." (PMID 34940056, 2021). "Comparison of CCN4 mRNA levels among diverse cancer types and adjacent normal tissue revealed significantly higher CCN4 expression in seven types of cancer (BRCA, DLBC, ESCA, GBM, HNSC, PAAD, and STAD)." (PMID 33833779, 2021). "Initially CCN4 was studied in the context of various cancer models." (PMID 39276419, 2024). "CCN4 (cellular communication network factor 4), a highly conserved, secreted cysteine-rich matricellular protein is emerging as a key player in the development and progression of numerous disease pathologies, including cancer, fibrosis, metabolic and inflammatory disorders." (PMID 38937782, 2024). "However, in breast, lung, and liver cancer, CCN4 appears to play an opposing role." (PMID 33833779, 2021). "Altered expressions of CCN1/CYR61, CCN2/CTGF, CCN3/NOV, and CCN4/WISP1 were found to correlate with clinical features, including venous invasion, cellular differentiation, TNM staging for malignant tumors, disease-free survival, and overall survival in HCC." (PMID 27829832, 2016). "Wnt1 inducible signaling pathway protein 1 (WISP1), also known as CCN4, is a target of Wnt1 and affects programmed cell death, cancer cell growth, extracellular matrix production, cellular migration, and mitosis." (PMID 26171319, 2015).
CCN4 also shares sentences with these, for which no sentence is quoted: lung carcinoma (22 papers); oral squamous cell carcinoma (16); glioblastoma (14); colon carcinoma (13); idiopathic pulmonary fibrosis (10); colorectal cancer (9); hepatocellular carcinoma (9); diabetes (8); esophageal cancer (8); Hypertension (6); breast tumors (4); lung injury (4); metabolic disorders (4); myocardial infarction (4); ovarian carcinoma (4); rheumatoid arthritis (4); Sepsis (4); asthma (3); colon adenocarcinoma (3); invasive breast carcinoma (3); liver disease (3); non-small cell lung carcinoma (3); pancreatic cancer (3); prostate adenocarcinoma (3); adenocarcinoma (2); bone cancer (2); cervical cancer (2); colitis (2); endometrial adenocarcinoma (2); head and neck carcinoma (2).
A further 75 diseases each share a sentence with CCN4 in 2 papers or fewer.